WWP1 (WW domain containing E3 ubiquitin protein ligase 1)
Diseases named in the same sentence as WWP1 in open-access papers (continued):
Sharing a sentence is not in itself a finding about the gene and the disease.
prostate carcinoma (19 papers, 2012 to 2025). A carcinoma that arises from epithelial cells of the prostate gland. "Because WWP1 has been associated with breast and prostate cancer progression, we sought to investigate the role of CYYR1 in cancer." (PMID 39059493, 2024). "It should be noted that a previous study reported an oncogenic role for WWP1 in targeting LATS for proteolytic degradation, and high expression levels of WWP1 have been implicated in worse prognostic outcomes in hepatocellular carcinoma and prostate cancer." (PMID 34404733, 2021). "In prostate cancer (PCa), WWP1 is a direct target of miR-452, which is downregulated in PCa patients." (PMID 39949609, 2024). "WWP1 negatively regulates this pathway by ubiquitinating and degrading critical components like Smad2 and TβRI, which in prostate cancer (PCa) results in WWP1 overexpression that inhibits TGF-β-induced gene expression and promotes cell proliferation." (PMID 39949609, 2024). "Mechanistically, miR-452 binds to the 3′-UTR of WWP1 to inhibit its expression, thereby reducing WWP1-mediated proliferation, migration, and invasion of prostate cancer cells." (PMID 38129384, 2023). "Bortezomib, a proteasome inhibitor approved for multiple myeloma, can inhibit WWP1, preventing oncogenesis and bone metastasis in prostate cancer." (PMID 38129384, 2023). "Bortezomib inhibited the mRNA and protein levels of WWP1 in prostate cancer cells, leading to cell growth suppression." (PMID 34226507, 2021). "Bortezomib was further reported to prevent bone metastasis of prostate cancer cells by inhibition of the WW domain containing E3 ubiquitin protein ligase 1 (WWP1) and Smurf ligases, which are frequently upregulated in patients with bone metastasis." (PMID 34831167, 2021). "WWP1 gene had copy number gain in 44% xenograft and cell lines that were obtained from prostate cancer." (PMID 34226507, 2021). "Vast evidence reveals that WWP1 is overexpressed in multiple cancer types, especially some breast and prostate cancers, while downregulated in several classes of carcinomas." (PMID 34712671, 2021). "Another study also revealed that WWP1 expression was increased in prostate cancer specimens compared with normal prostate specimens and PIN specimens." (PMID 34226507, 2021). "Overexpression of miR-452 suppressed migratory and invasive capability of prostate cancer cells partly via downregulation of WWP1." (PMID 34226507, 2021). "Knockdown of WWP1 inhibited proliferation of prostate cancer cells and suppressed TFG-β-induced growth." (PMID 34226507, 2021). "Specifically, miR-452 expression was decreased in prostate cancer patients, while WWP1 was highly expressed in patients with prostate cancer." (PMID 34226507, 2021). "Bortezomib, a proteasome inhibitor, prevented development and bone metastasis via suppression of WWP1, Smurf1, and Smurf2 in prostate cancer." (PMID 34226507, 2021). "Genetic amplification and overexpression of the WWP1 E3 ubiquitin ligase, which degrades KLF5 protein, also frequently occur in human prostate cancer, causing excess protein degradation and insufficiency of KLF5." (PMID 25896712, 2015). "Here we report a novel interaction of ezrin with a HECT E3 ubiquitin ligase, WWP1/Aip5/Tiul1, a potential oncogene that undergoes genomic amplification and overexpression in human breast and prostate cancers." (PMID 22629406, 2012). "Since WWP1 depletion has been shown to decrease cell growth of breast and prostate cancer cells in similar assays, we speculate that the effect of CYYR1 on cell growth may be mediated by WWP1 degradation." (PMID 39059493, 2024). "Prior research has indicated that WWP1 is abnormally amplified in prostate cancer and gastric cancer, and may be considered as an oncogene to promote tumor development." (PMID 39049965, 2024).
prostate carcinoma (continued). "WWP1 interacts with the PY2 motif of KLF5 (at codon 293-348) to promote its ubiquitination and degradation in breast and prostate cancers, suggesting that WWP1 might promote tumorigenesis via KLF5 downregulation (Fig. 5A3,)." (PMID 38129384, 2023). "WWP1 is a NEDD4 family protein whose altered expression has been associated with both oncogenic and tumour-suppressive functions in a number of cancers, including osteosarcoma, gastric cancer, prostate cancer, melanoma, oral cancer and breast cancer." (PMID 35204725, 2022). "Moreover, higher expression of WWP1 was observed in metastatic prostate cancer compared with primary prostate cancer." (PMID 34226507, 2021). "Depletion of WWP1 reduced the migration and invasion of prostate cancer cells." (PMID 34226507, 2021). "In prostate cancer, a mutant of WWP1 was found to be correlate with pathogenesis." (PMID 33418880, 2021). "WWP1 has been reported to be a direct target of miR-452 in prostate cancer cells." (PMID 34226507, 2021). "Amplification and over-expression of WWP1 has been found in breast and prostate cancers." (PMID 23573293, 2013). "Further examining the correlation between levels of LATS1 and WWP1 using clinical breast and prostate cancer may provide further in vivo data regarding how dysregulation of these two proteins are involved in the development of human cancers." (PMID 23573293, 2013). "Targeting miR-452 might be a potential approach to regulating WWP1 for treating prostate cancer." (PMID 34226507, 2021). "Hence, WWP1 is frequently overexpressed in breast and prostate cancers." (PMID 33418880, 2021). "I3C inhibition of WWP1 was also found to reactivate the tumour suppressor PTEN and suppress MYC-dependent growth promoting activities in prostate cancer cells that had high WWP1 expression." (PMID 35204725, 2022). "Estrogen promoted the interactions between ERβ, WWP1 and KLF5, leading to promotion of KLF5 degradation in prostate cancer cells." (PMID 34226507, 2021). "The growth promoting activity of WWP1 has been demonstrated in MDCK canine kidney epithelial cells, PC-3 prostate cancer cells, SC3, CA922, CAL27, TW206, SAS and OECM-1 oral cancer cell and HCT116 colon cancer cells." (PMID 26506518, 2015). "WWP1 negatively regulates the TGF-β tumor suppressor pathway by targeting components like Smad2 and TβRI for ubiquitination and degradation, thereby enhancing prostate cancer (PCa) cell proliferation (Massagué and Like, 1985)." (PMID 39949609, 2024). "By contrast, WWP1 may negatively regulate PTEN in cancer; indeed, WWP1 directly ubiquitinates PTEN and inhibits its dimerization and translocation to the cellular membrane in human prostate cancer." (PMID 41009733, 2025). "Aronchik and his colleagues reported that indole-3-carbinol (I3C), a compound derived from cruciferous vegetables, could inhibit the functions of NEDD4-1 and WWP1 through targeting the HECT domain, thus abrogating the proliferation and metastasis of melanoma or prostatic carcinoma." (PMID 35264565, 2022). "All in all, WWP1-mediated K27 pUb of PTEN may promote tumorigenesis of colon and prostate cancers." (PMID 34712671, 2021). "For example, in the Hippo pathway, WWP1 executes its tumorigenic function by targeting LAST1 for degradation, while two other components of this pathway, YAP and TAZ, antagonize WWP1-mediated degradation of KLF5 and consequently promote growth and metastasis of some breast and prostate cancers." (PMID 34712671, 2021).
cardiac hypertrophy (13 papers, 2020 to 2025). "Finally, we identified that ANF and miR-23a are downstream targets of circRNA wwp1, suggesting that circRNA wwp1 exerts inhibitory roles of cardiac hypertrophy via down-regulation of ANF and miR-23a, which underlying the potential mechanisms whereby circRNA regulates cardiac hypertrophy." (PMID 32023551, 2020). "WWP1 is significantly upregulated in both the aortic constriction model and the hearts of patients with cardiac hypertrophy." (PMID 41362701, 2025). "Genetic knockout of WWP1 significantly alleviated myocardial hypertrophy and dysfunction, suggesting its central regulatory role in pathological myocardial remodeling." (PMID 41362701, 2025). "WWP1 also promotes atypical K27-linked ubiquitin multichain assembly on DVL2 and exacerbates cardiac hypertrophy via the DVL2/CaMKII/HDAC4/MEF2C pathway." (PMID 38674024, 2024). "WWP1 triggers excessive cardiomyocyte inflammation after MI, as well as exacerbating cardiac hypertrophy." (PMID 38674024, 2024). "WWP1 promotes K27-linked ubiquitin multichain assembly on DVL2, exacerbating cardiac hypertrophy via the DVL2/CaMKII/HDAC4/MEF2C pathway." (PMID 39949609, 2024). "WWP1 inhibits the signal transduction by regulating the polyubiquitin associated with Kmur27 to stabilize DVL2, thereby treating myocardial hypertrophy." (PMID 37507372, 2023). "WWP1 promotes pressure overload-induced cardiac hypertrophy by inducing K27-mediated polyubiquitination of dishevelled segment polarity protein 2 (DVL2), thereby enhancing the DVL2/CaMKII/HDAC4/MEF2C signaling pathway." (PMID 38129384, 2023). "WW domain-containing E3 Ub- protein ligase 1 (WWP1) is not only a therapeutic target for myocardial remodeling, but also a potential target for cardiac hypertrophy." (PMID 37507372, 2023). "Recent studies have reported that WWP1 is involved in cardiac hypertrophy 20, atrial fibrosis 34, arrhythmogenesis 11 and heart failure (HF) with a preserved ejection fraction (EF; HFpEF) 12; however, these are non-ischemic cardiovascular diseases." (PMID 36593958, 2023). "Additionally, WWP1 stabilizes disheveled segment polarity protein 2 (DVL2) through K27-linked polyubiquitination, a process critical for cardiac hypertrophy." (PMID 39949609, 2024). "WWP1 promotes cardiac hypertrophy and remodeling in response to simulated microgravity, although the specific mechanisms by which WWP1 exerts its effect remain unknown." (PMID 38129384, 2023). "Pressure overload-induced heart hypertrophy was relieved in WWP1 knockout (KO) mice." (PMID 34733849, 2021). "Also, in our previous research, we identified WWP1 as a novel regulator of pathological cardiac hypertrophy and heart failure." (PMID 34733849, 2021). "E3 ligases, which determine substrate specificity in ubiquitination, are increasingly recognised for their role in pathological cardiac hypertrophy, with ligases such as TRAF6, TRIM16 and WWP1 being identified as key contributors." (PMID 40753540, 2025). "circRNA wwp1 exerts inhibitory roles of cardiac hypertrophy via down-regulation of ANF and miR-23a in isoproterenol hydrochloride-induced cardiac hypertrophy." (PMID 33928139, 2021). "Our previous research found that E3 ubiquitin ligase WWP1 can stabilize DVL2 by catalyzing K27-linked polyubiquitination, and DVL2 positively correlated with WWP1 hypertrophic heart and mediated the regulation of the CaMKII/HDAC4/MEF2C axis in cardiac hypertrophy by WWP1." (PMID 34733849, 2021).
gastric cancer (10 papers, 2015 to 2025). A primary or metastatic malignant neoplasm involving the stomach. "In gastric cancer, elevated expression levels of both WWP1 and WWP2 are significantly associated with worse OS, particularly in early-stage tumors, suggesting a role for these proteins in the early metastatic spread of gastric cancer." (PMID 39949609, 2024). "In gastric cancer (GC), downregulated miR-129-5p and miR-129-3p were associated with WWP1 expression." (PMID 39949609, 2024). "Consistently, WWP1 expression was negatively associated with miR-584-5p expression in gastric cancer specimens." (PMID 34226507, 2021). "For example, WWP1 (WW domain-containing E3 ubiquitin protein ligase 1) is frequently overexpressed in papillary thyroid cancer and breast, prostate, and gastric cancers." (PMID 40002221, 2025). "WWP1 contributes to the growth and proliferation of gastric cancer, CRC, oral cancer, and PTC through the PI3K/AKT pathway." (PMID 38129384, 2023). "MiR-129-2-3p plays a pivotal role in gastric cancer by restraining its migration and proliferation in vitro and slowing down gastric cancer growth in vivo via the inhibition of WWP1." (PMID 36312756, 2022). "Overexpression of WWP1 enhanced proliferation and migration in gastric cancer cells and facilitated tumor growth in vivo." (PMID 34226507, 2021). "Upregulation of WWP1 abolished the effects of miR-584-5p overexpression on gastric cancer cells, while depletion of WWP1 impaired the function of miR-584-5p inhibitors." (PMID 34226507, 2021). "It has been identified that miR-129-5p and miR-129-3p targeted WWP1 in gastric cancer cells." (PMID 34226507, 2021). "High expression of WWP1 at mRNA and protein levels was also reported in gastric carcinoma tissues, which was associated with TNM stage, LNM, and invasive depth and poor prognosis in patients with gastric cancer." (PMID 34226507, 2021). "Moreover, deficiency of WWP1 resulted in G0/G1 phase arrest and apoptosis of MKN-45 and AGS gastric cancer cells via inactivation of the PTEN/Akt pathway." (PMID 34226507, 2021). "Furthermore, miR-129-5p and miR-129-3p repressed cell proliferation and migratory ability via suppression of WWP1 in gastric cancer." (PMID 34226507, 2021). "In addition, WWP1 is frequently amplified in breast, prostate, oral, hepatocellular carcinoma, and gastric carcinoma cells, suggesting the crucial impact of WWP1 in tumorigenesis." (PMID 32259050, 2020). "Moreover, WWP1 was identified as a direct downstream target of miR-584-5p in gastric cancer cells." (PMID 34226507, 2021). "In gastric cancer, miR-129-5p targets two sites in WWP1 CDS whereas miR-129-3p targets the 3′-UTR of WWP1 to inhibit WWP1-mediated proliferation and migration in vitro and tumor growth in vivo." (PMID 38129384, 2023). "miR-584-5p, which is downregulated in gastric cancer cells and tissues, targets the 3′-UTR of WWP1 to promote its degradation and inhibit its proliferation, thus inducing apoptosis." (PMID 38129384, 2023). "Mechanistically, miR-584-5p decreased WWP1 expression, leading to accelerating senescence and activating TGF-β pathway in gastric cancer." (PMID 34226507, 2021). "Small molecules such as Heclin (a non-specific HECT E3 inhibitor) and Indole-3-carbinol (I3C; inhibitor against NEDD4-1 and WWP1 catalytic HECT domains) are capable of stabilizing PTEN, reducing Akt phosphorylation, and impairing cell viability in models of gastric cancer and melanoma." (PMID 40002221, 2025). "WWP1 can ubiquitinate TGF-β receptor-I (TβR-I) and SMAD4, leading to negative regulation of TGF-β signaling, which promotes the proliferation of prostate and gastric cancer cells." (PMID 38129384, 2023).
acute myeloid leukemia (8 papers, 2019 to 2025). Acute myeloid leukemia (AML) is a group of neoplasms arising from precursor cells committed to the myeloid cell-line differentiation. "The cyclin/CDK protein kinase inhibitor, p27, can be ubiquitinated by WWP1, resulting in cell proliferation and growth of acute myeloid leukemia (AML)." (PMID 34712671, 2021). "Deregulation of WWP1 expression in acute myeloid leukemia (AML) blasts might accelerate TXNIP proteasomal degradation, thus increasing the ability of thioredoxin to buffer ROS, and ultimately favoring leukemic cell survival." (PMID 39364720, 2025). "In acute myeloid leukemia (AML), WWP1 inactivation resulted cell cycle arrest and autophagy, which inhibited AML cell survival and growth in mice." (PMID 39014007, 2024). "In acute myeloid leukemia (AML), elevated WWP1 expression reduces p27 levels, promoting cell cycle progression and enhancing AML cell survival." (PMID 39949609, 2024). "WWP1 knockdown in acute myeloid leukemia (AML) cells indeed leads to autophagy induction, which is accompanied by increased total levels of LC3 and ATG7 and accumulation of lipidated LC3." (PMID 31441992, 2019). "WWP1 is indeed aberrantly expressed in a variety of human cancers such as prostate, breast, gastric and hepatocellular carcinomas as well as acute myeloid leukemia (AML)." (PMID 39364720, 2025). "WWP1 expression was augmented in acute myeloid leukemia (AML) patients and inactivation of WWP1 inhibited the proliferation of AML cells and tumor growth in mice." (PMID 34226507, 2021).
COVID-19 (8 papers, 2021 to 2025). A disease caused by infection with severe acute respiratory syndrome coronavirus 2. "Importantly, rare germline activating variants in the NEDD4 and WWP1 genes (HECT E3 ligase family members) are associated with severe COVID-19 cases." (PMID 38709105, 2024). "Moreover, they found that several rare variants in the NEDD4 E3 ubiquitin-protein ligase (NEDD4) and WW domain containing E3 ubiquitin-protein ligase 1 (WWP1) genes are associated with severe cases of COVID-19, when compared to asymptomatic controls." (PMID 37259386, 2023). "Moreover, we found that several rare variants in the NEDD4 E3 ubiquitin protein ligase (NEDD4) and WW domain containing E3 ubiquitin protein ligase 1 (WWP1) genes are associated with severe cases of COVID-19, when compared to asymptomatic controls." (PMID 36522315, 2022). "We utilized the WWP1 K740N mutant as a control for the WWP1 N745S COVID-19 associated mutant." (PMID 33762578, 2021). "Importantly, rare germline activating variants in the NEDD4 and WWP1 genes are associated with severe COVID-19 cases." (PMID 33762578, 2021). "In addition, promoted WWP1 regulates ciliary dynamics via the Hedgehog receptor Smo, and a dysregulated Hedgehog pathway is one of the molecular mechanisms underlying COVID-19-induced pulmonary fibrosis." (PMID 38674024, 2024). "Additionally, germline variants of WWP1 are significantly associated with severe cases of COVID-19." (PMID 38129384, 2023). "Rare germline variants of WWP1 and NEDD4 can promote viral egress and are associated with severe COVID-19 cases." (PMID 38129384, 2023). "We then studied the expression of NEDD4 and WWP1 at protein level taking advantage of a COVID-19 mouse model and of available human lung specimens from infected patients necropsy." (PMID 33762578, 2021). "Moreover, promoted WWP1 regulates ciliary dynamics via the Hedgehog receptor Smoothened (Smo), and a dysregulated Hedgehog pathway is one of the molecular mechanisms of COVID-19-induced pulmonary fibrosis." (PMID 38674024, 2024). "Expression analysis has revealed that WWP1 and NEDD4 are overexpressed in COVID-19-infected patients." (PMID 38129384, 2023). "Interestingly, however, in PCR positive COVID-19 human lungs, NEDD4 and WWP1 were downregulated everywhere except in regions that expressed SARS-CoV-2 proteins." (PMID 33762578, 2021). "We found that WWP1, WWP2, SMURF1, and NEDD4 mRNA are overexpressed in COVID-19 vs. SARS-CoV-2 negative patients in nasopharyngeal and oropharyngeal swab cells, as well as in the lung of affected patients and in mouse models of COVID-19." (PMID 33762578, 2021). "We next hypothesized that if HECT-E3 ligases are indeed functionally relevant for the viral life cycle of COVID-19, Indole-3-carbinol (I3C), a natural NEDD4 and WWP1 inhibitor from Brassicaceae, might display a direct antiviral effect." (PMID 33762578, 2021). "We finally evaluated whether selective inhibition of HECT proteins by a natural NEDD4 and WWP1 inhibitor from Brassicaceae displayed anti-SARS-CoV-2 activity, thus providing preclinical support for the possible development of clinical trials using this natural inhibitor in COVID-19 patients." (PMID 33762578, 2021). "In PCR negative COVID-19 human lungs, the basal expression of NEDD4 and WWP1 was high." (PMID 33762578, 2021). "NEDD4 (FC = + 2.06, p ≤ 0.005), WWP1 (FC = + 1.85, p ≤ 0.0005), WWP2 (FC = + 4.11; p < 0.005) and SMURF1 (FC = + 1.7, p ≤ 0.05) showed a significant overexpression in nasopharyngeal and oropharyngeal swabs of COVID-19 positive patients compared to negative patients." (PMID 33762578, 2021).